MUS81 (MUS81 structure-specific endonuclease subunit)
Diseases named in the same sentence as MUS81 in open-access papers (continued):
Sharing a sentence is not in itself a finding about the gene and the disease.
cancer (continued). "Notably, recent studies have found that the expression level of MUS81 is closely related to the evolution of various cancers." (PMID 34513672, 2021). "According to our in silico PPI analysis, MUS81 is predicted to interact directly or indirectly with other cancer-related genes, which might also impact the gene penetrance." (PMID 32443704, 2020). "EME2 in conjunction with MUS81 initiate replication fork restart, indicating its increased expression could be exploited by cancer cells for enhanced DNA replication." (PMID 32457837, 2020). "Deregulated expression of MUS81 was reported in serous ovarian and prostate cancer cells." (PMID 32443704, 2020). "For example, Mus81 cleavage of the displacement loop (D-loop), the initial recombination intermediate that form in broken replication forks, limits mutagenic template switches that propels genome instability in cancers." (PMID 30558228, 2018). "In other contexts, Mus81 activity can contribute to survivability of cancer cells." (PMID 30558228, 2018). "Inactivation of the Mus81 gene in mice has no major deleterious consequences for embryonic development, although cancer susceptibility has been reported." (PMID 26415217, 2015). "Future work will be necessary to explore the possible potential of Mus81-Eme1 as a tumour marker and to gain information that may help in the improvement of anti-cancer therapy." (PMID 23901010, 2013). "Mice homozygous for the Mus81Δex3-4 mutation showed no expression of Mus81 protein, and displayed elevated levels of spontaneous genomic instability and cancer predisposition." (PMID 21625617, 2011). "Given the importance of Chk2 and Mus81 in DNA damage signaling and repair respectively, we have examined the effect of their dual inactivation on lymphoid cell differentiation, DNA damage response and cancer." (PMID 21625617, 2011). "Recent data indicated Mus81's role in maintaining genomic integrity and suppressing cancer." (PMID 21625617, 2011). "Thus, our data indicate that an important role for Chk2 is maintaining lymphocyte development and that dual inactivation of Chk2 and Mus81 remarkably inhibits cancer." (PMID 21625617, 2011). "Importantly, since compounds inducing TOP1-mediated DPCs are currently used in cancer treatment, understanding the underlying mechanism of the repair pathway is essential for improving the efficiency of combination therapy with TDP1 and MUS81 inhibitors." (PMID 37194054, 2023). "Therefore, MUS81 could be envisioned as the molecular landscape of highly replicating cancer cells and the target in sensitizing the cancer cells to anti-cancer chemicals such as arsenic." (PMID 31803609, 2019). "Importantly, MUS81 expression was found significantly decreased in human hepatocellular carcinomas, and this reduced expression correlates with a poor prognosis for patients with this cancer." (PMID 21625617, 2011). "Finally, we note that it will be of interest to determine whether MUS81 function/dysfunction influences how normal and cancer cells respond to Chk1-targeting drugs that are being developed as anti-cancer agents." (PMID 21858151, 2011). "When WRN nuclease activity is inhibited, MRE11 will cleave unprotected forks, generating mus81-dependent DSBs, while increasing NHEJ and chromosomal instability, leading to cancer cell death." (PMID 39759116, 2025). "Our data indicate that MUS81 and TDP1 play independent roles in the repair of CPT-induced lesions, thus representing new therapeutic targets for cancer cell sensitisation in combination with TOP1 inhibitors." (PMID 37194054, 2023). "Thus, MUS81 could be presented as a novel molecular target for future anti-cancer treatment." (PMID 34527278, 2021).
cancer (continued). "In various types of cancer cells, downregulation of XPF or MUS81 increases sensitivity to chemotherapeutic drugs cells via CHK1 pathway activation or stimulation of apoptosis." (PMID 30558228, 2018). "The most frequently amplified genes across the pan-cancer atlas were BRIP1 (HDR, 8.04%), POLB (BER, 6.54%), MUS81 (HDR, 6.42%), NBN (HDR, 6.31%), and EXO1 (MMR, 6.26%), while the most frequently deleted genes were BRCA2 (HDR, 6.44%), XRCC2 (HDR, 6.38%), and CUL5 (NER, 6,28%)." (PMID 36081518, 2022). "Unlike its protective role in BRCA-defective tumors, MUS81 mediates chromosome shattering and apoptosis in cancer cells with microsatellite instability and a defect in the Werner syndrome helicase WRN." (PMID 36203968, 2022). "A further understanding of the precise mechanisms of MUS81 and the interactions among DDR pathways in discrepant cancers may pave the way toward improved cancer therapeutic strategies." (PMID 33791310, 2021). "Mus81 is also required in humans for telomere recombination to allow proliferation of telomerase-negative cancer cells." (PMID 23071463, 2012).
tumor (18 papers, 2008 to 2024). "IHC studies indicated that after treatment with talazoparib, tumor tissues from the MUS81-deficient group showed lower Ki67 expression, suggesting lower proliferation ability compared to that of the parental xenograft group." (PMID 35480096, 2022). "The reason for the discrepant performance of murine MUS81 in tumor predisposition is still unclear." (PMID 33791310, 2021). "Interestingly, three sporadic tumor samples presented a MUS81 c.1292G>A variant in heterozygosis." (PMID 32443704, 2020). "This research provides evidence for predicting drug resistance of tumor patients to Olaparib by MUS81, enabling MUS81 to become a novel gene target for the treatment of CRPC." (PMID 35910852, 2022). "As expected, MUS81 knockdown tumor cells showed higher expression of γ-H2AX than control cells in response to talazoparib." (PMID 35480096, 2022). "After treatment with MK1775 or solvent for 16 d, tumor volume was significantly decreased in the MUS81 knockdown group." (PMID 34625086, 2021). "The analysis of all exons of MUS81 in the tumor sample from patient M1 confirmed the presence of both germline variants c.1292G>A and c.344C>T." (PMID 32443704, 2020). "We evaluated MUS81 expression in three tumor tissues positive for MUS81 c.1292G>A (p.R431H) (BC from M4, BC from M5, and TC from M1) and three MUS81 wild-type tissues (one normal thyroid, one normal breast, and one BC)." (PMID 32443704, 2020). "We also sequenced all exons of MUS81 from the tumor DNA of patient M1, available from fresh frozen tissue, to investigate other variants in the TC tissue sample." (PMID 32443704, 2020). "Adjusting for prognostic variables, age, stage and gender, we studied the protein levels of XPF and MUS81 in pre-treatment tumor biopsies to derive potential relationships with clinical outcomes." (PMID 29739952, 2018). "The IHC results also confirmed the activation of CHK1/CDC25A/CDK2 pathway in xenograft tumor generated from Mus81‐inhibited HepG2 cells under EPI treatment." (PMID 26714930, 2016). "Herein, we provide evidence demonstrating that INDO-mediated COX2 inhibition augments MUS81-mediated cytoplasmic tumor DNA accumulation and cGAS/STING/type I IFN, which restored tumor immune surveillance via potent antitumor innate and adaptive immune responses in irradiated 4T1 TNBC tumors." (PMID 38912586, 2024). "Therefore, treatment of mismatch repair-defective tumors with inhibitors of both WRN and MUS81 would be counterproductive as it would block MUS81-dependent tumor cell killing." (PMID 38069223, 2023). "There is, however, a different voice suggesting that murine MUS81 is unnecessary for tumor suppression, based on evidence that no increased sign of tumors was detected in MUS81-deficient mice during a 15-month monitoring." (PMID 33791310, 2021). "Of note, MUS81 was described as a tumor suppressor with a haploinsufficient phenotype." (PMID 32443704, 2020). "Our discovery that MUS81 inactivation is lethal when combined with BRCA2 deficiency identifies MUS81 as a potential target for the development of drugs that could selectively eliminate BRCA2-compromised cells and tumours." (PMID 28714477, 2017). "Thus, determining the role of MUS81 in tumor suppression requires further studies." (PMID 33791310, 2021). "Interestingly, MUS81 is helpful for tumor survival in some cases but lethal to them in other cases." (PMID 33791310, 2021). "If the W823* and E1517* truncating variants are causative mutations and if these truncated SLX4 proteins are expressed, the differential sensitivity to ICL and other agents may indicate that the SLX4 function associated with MUS81 and/or SLX1 is essential for tumor suppression in the breast tissue." (PMID 23840564, 2013). "During this process, the DNA endonuclease MUS81/EME1 complex and PARP-dependent DNA repair pathways mediate shedding and cytosolic accumulation of genomic tumor DNA." (PMID 38912586, 2024).
tumor (continued). "Correlation of pre-treatment tumor mRNA expression with XPF and MUS81 protein expression, measured by IHC composite score, showed a statistically significant association between ERCC1 mRNA expression and XPF protein levels (P = 0.041) in the clinical samples." (PMID 29739952, 2018). "The expression of MUS81 could be upregulated in CRPC, which mediated the growth of tumor cells through ATM." (PMID 35910852, 2022). "MUS81 is an important DDR factor and a relevant tumor marker." (PMID 36203968, 2022). "MUS81 was found to cleave DNA in prostate cancer cells, inducing cytosolic DNA that serves as a prostate tumor marker and promotes STING-dependent immune recognition to drive host rejection of tumor cells in vivo." (PMID 36203968, 2022). "Additionally, the effects of silencing MUS81 on enhancing CPT sensitivity and inhibiting tumor metastasis were also confirmed by micro-MRI." (PMID 31803609, 2019). "Surprisingly, however, Mus81−/− mice are viable and do not show obvious defects, apart from increased tumor incidence, despite the fact that embryo fibroblasts from these knockout mice accumulate chromosomal aberrations." (PMID 26415217, 2015). "Nonetheless, c.1292G>A might explain the low or negative expression of MUS81 in the tumor, as shown in immunohistochemistry analysis." (PMID 32443704, 2020).
infection (3 papers, 2011 to 2025). The state of being infected such as from the introduction of a foreign agent such as serum, vaccine, antigenic substance or organism. "To eliminate another possibility that knocking out Mus81 might have affected HBV entry, a step preceding cccDNA formation during de novo infection, we conducted hepatitis delta virus (HDV) infection in HepG2-NTCP Mus81 K.O. cells." (PMID 39913382, 2025).
MUS81 also shares sentences with these, for which no sentence is quoted: aortic aneurysm (1 paper); benign prostatic hyperplasia (1); breast tumor (1); B‐cell lymphomas (1); esophageal adenocarcinoma (1); hearing loss (1); leukemia (1); malignant astrocytoma (1); osteosarcoma (1); pancreatic tumour (1).